IL6 (interleukin 6)
Diseases named in the same sentence as IL6 in open-access papers (continued):
Sharing a sentence is not in itself a finding about the gene and the disease.
prostate carcinoma (continued). "Another study implemented on neuroendocrine differentiation in prostate cancer cells revealed that knockdown of REST activates the IL-6-induced autophagy, while IL-6-induced neuronal cell morphology changes in prostate cancer cells were significantly inhibited due to the REST overexpression." (PMID 34819125, 2021). "Likewise, SDF-1 and IL-6 released by CAFs and tumor cells in prostate cancer, promotes the polarization of macrophages into an M2 phenotype." (PMID 34858425, 2021). "For instance, in mouse model of prostate cancer, depression is illuminated to increase the infiltration of myeloid cells and interleukin-6 (IL-6) expressions via mediating sympathetic neuropeptide Y (NPY) signaling pathway and subsequently enhances the tumor growth." (PMID 33411223, 2021). "Interestingly, one study shows that Meth-AEA induces IL-6 secretion by prostate cancer cells, and this effect is inhibited by CB2 receptor antagonist SR144528 and not by CB1 receptor antagonist rimonabant." (PMID 32295577, 2020). "In addition, IL-6 from infiltrated preadipocytes and TAMs further promotes migration and invasion of prostate cancer cells expressing a low level of SFMBT2." (PMID 32971847, 2020). "Here we show that IL-6 produced by T. vaginalis infection in prostate epithelial cells induces M2 polarization of macrophages and these macrophages promote proliferation of prostate cancer cells." (PMID 32196489, 2020). "Moreover, increased IL-6 from infiltrated preadipocytes and TAMs further enhance migration and invasion of prostate cancer cells." (PMID 32971847, 2020). "In a prostate cancer-induced cachexia study, an IL-6 antagonist alleviated weight loss but did not inhibit tumor growth." (PMID 32929072, 2020). "Moreover, CAFs isolated from prostate carcinomas produce higher amounts of other cytokines namely, pro-inflammatory cytokines, interleukin-6 (IL6) and bone morphogenetic factor (BMP6), thereby promoting tumor progression." (PMID 32754615, 2020). "IL6/JAK/STAT3 axis is known to drive proliferation in prostate cancer cells." (PMID 33284790, 2020). "Furthermore, IL-6 from infiltrated preadipocytes and TAMs promotes migration and invasion of prostate cancer cells." (PMID 32971847, 2020). "In addition, IL-6 promotes prostate cancer cell growth, invasion, migration, and epithelial-mesenchymal transition (EMT), resulting in metastasis." (PMID 32971847, 2020). "Moreover, increased IL-6 from infiltrated preadipocytes and TAMs promoted migration and invasion of prostate cancer cells expressing a low level of SFMBT2." (PMID 32971847, 2020). "In Pten-deficient model mice for prostate cancer, a high-fat diet mediated inflammation-induced M2 TAM differentiation and expansion of MDSCs, accelerated IL-6 secretion, and facilitated tumor growth via IL-6/STAT3 signaling pathway." (PMID 32824865, 2020). "Thus, immunotherapies focused on the inhibition of either MDSCs recruitment or the inhibition of other mediators that sustain MDSCs immunosuppressive effect (e.g., IL-6 and IL-23) can be a promising therapeutic strategy for prostate cancer patients." (PMID 32849585, 2020). "In addition, IL-6 expression was proportionally related to a high Gleason score of ≥8 and increased in prostate cancers expressing a low level of SFMBT2." (PMID 32971847, 2020). "Hsp27 is required for IL-6-mediated EMT via STAT3/Twist signaling in prostate cancer." (PMID 32315283, 2020). "IL-6 might increase the number of local MDSCs and promote the proliferation of prostate cancer cells via signal transducer and activator of transcription 3 (STAT3) pathways." (PMID 30736371, 2019). "Furthermore, 167 prostate cancer biopsy specimens were analyzed in terms of correlations of IL-6 and CD44 levels with clinical patient characteristics." (PMID 31315262, 2019).
prostate carcinoma (continued). "Objectively measured IL-6 expression levels in prostate cancer biopsy tissues could be of additional value with respect to determining the biological aggressiveness of prostate cancer and may be useful to guide treatment decisions." (PMID 31315262, 2019). "Therefore, activating IL-6/STAT3 signaling plays an important role in the induction of CD44-positive prostate cancer." (PMID 31315262, 2019). "In prostate cancer, loss of p62 in the stromal fibroblasts impairs mTORC1 activation, which results in a reduced metabolic detoxification capacity and the secretion of the prosurvival inflammatory cytokine IL‐6, which sustains the growth and invasiveness of the neighboring prostate cancer cells." (PMID 30499183, 2019). "Based on our study, IL-6 is a potential biomarker of aggressive prostate cancer." (PMID 31315262, 2019). "Of the 167 prostate cancer patients, 67 (40%) showed overexpression of IL-6." (PMID 31315262, 2019). "In prostate cancer cell-based and xenograft models, IKKε promoted proliferation and tumor growth along with IL-6 expression in a manner dependent on the nuclear accumulation of the transcription factor C/EBP-β, which regulates genes involved in metastasis and survival of prostate cancer cells." (PMID 30791439, 2019). "Multiple pathways have been shown to induce NED in prostate cancer cells in vitro, including androgen deprivation, interleukin-6 (IL-6) treatment, Wnt pathway activation, EGF signaling pathways, activation of the cyclic adenosine 3′, 5′-monophosphate (cAMP) signaling pathway, or ionizing radiation." (PMID 29721191, 2018). "RKIP overexpression in breast and prostate cancer cell lines was shown to inhibit cellular Src (c-Src) autophosphorylation and activation, as well as interleukin 6 (IL-6)-, janus kinase 1/2 (JAK1/2)-, and activated Raf-mediated STAT3 tyrosine and serine phosphorylation, needed for STAT3 activation." (PMID 30149591, 2018). "Additionally, it was reported that AR transactivation can be activated through IL-6 in human prostate cancer (LNCaP) cells in an androgen-independent manner." (PMID 30545141, 2018). "IL-6 also downregulated the Maspin tumor suppressor in prostate cancer cell lines." (PMID 30558204, 2018). "In addition, TLR downstream cytokines IL-6, IL-8, and IL-10 mediate prostate cancer development and disease progression." (PMID 29928275, 2018). "Prior to determine if this effect is associated with the JAK2/STAT3, protein extracts from prostate cancer cells under the influence of IL-6 with and without the treatment of anti-IL-6R antibody were examined for the phosphorylation of JAK2 and STAT3." (PMID 30134795, 2018). "Additional findings supporting the hypothesis of C. acnes as a trigger of prostate cancer development comes from in vitro studies reporting an increased secretion of IL6 and CXCL8 by prostate epithelial cells infected with C. acnes." (PMID 30473726, 2018). "Recent evidence suggests that IL-6 may have a crucial role in prostate cancer progression through autocrine on tumor cells or paracrine activity on normal cells in the tumor microenvironment." (PMID 30134795, 2018). "Notably, increased IL-6 and IL-6R expression has been observed in prostate cancer epithelial cells and high-grade PIN." (PMID 29928275, 2018). "Moreover, MMSET interacts with NF-κB directly to activate the expression of NF-κB target genes (including interleukin-6, vascular endothelial growth factor A, cyclin D, Bcl-2 and Survivin) in prostate cancer cells." (PMID 29796186, 2018). "Since we employed PBMCs and prostate cancer cells in the study, IL-6 was used as the stimulant." (PMID 29868029, 2018). "The link between IL-6 and prostate cancer progression has been well established." (PMID 28077171, 2017).
prostate carcinoma (continued). "Expression of several cytokines in normal and malignant tissue is under control of nuclear factor kappa B. It is particularly important that interleukins (IL) are involved in regulation of many functions in prostate cancer, and IL-6 is highly expressed in castration-resistant tumors." (PMID 29214142, 2017). "In addition, a recent report showed that inhibition of IL-6/STAT3 signaling in a phosphatase and tensin homolog (PTEN)-deficient prostate cancer model promotes cancer progression." (PMID 28264478, 2017). "IL-6 has an anti-apoptotic effect on many types of cancer cells, including prostate cancer cells." (PMID 28292326, 2017). "Other data show that there is an inverse correlation between the expression of SOCS-3 and IL-6-induced phosphorylation of STAT3 in prostate cancer cells; furthermore, downregulation of SOCS-3 by a short interfering RNA approach resulted in inhibition of proliferation and an increased apoptotic rate." (PMID 29234375, 2017). "In addition, we discuss the roles of interleukin-6 and receptor activator of nuclear factor kappa-B ligand in modulating prostate cancer progression." (PMID 28292326, 2017). "Furthermore, it is revealed that endothelial cells within the prostate cancer microenvironment secreted IL-6, resulting in the downregulation of androgen receptor (AR) signaling in prostate cancer cells, which enhance the invasion of cancer cells." (PMID 29197379, 2017). "In addition to these clinical observations, in vitro cellular studies have shown that IL-6 modulates the growth of prostate cancer cells." (PMID 28292326, 2017). "In addition, IL-6-driven metastasis of prostate cancer was predominantly mediated by STAT3 signaling." (PMID 28783760, 2017). "In addition to the effect of enhancing cell proliferation, IL-6 also enhances other aspects of prostate cancer." (PMID 28292326, 2017). "In last years, it was observed that IL-6 play a crucial role in MDR (multi drug resistance) processes; in fact stimulation of androgen sensitive and insensitive prostate cancer cells with IL-6 determine, trough nuclear factor kappaB (NF-kappaB) activation, induce resistance to docetaxel treatments." (PMID 28389628, 2017). "In addition, immunohistochemical comparison between normal and prostate cancer using paraffin embedded sections show a higher degree of IL-6 staining in prostate cancer than those in perinormal tissue sections." (PMID 28467474, 2017). "This is demostrated by its capacity to lower IL-6 in prostate cancer cell line and PBMCs." (PMID 28356100, 2017). "The capacity of honey observed in this study, (both arid and non-arid region varieties) to significantly reduce the population of PC-3 cells and reduce its capacity to secrete IL-6, enables us to suggest a possible anti-tumor effect for honey in prostate cancer." (PMID 28356100, 2017). "Osteocalcin activation of GPRC6A may indirectly promote androgen synthesis through stimulation of IL-6, a cytokine that can promote androgen synthesis in prostate cancer cells through enhancing AKR1C3 transcription." (PMID 28659174, 2017). "In the present study, we validated the impact of IKKε depletion on the in vitro proliferation of castrate-resistant prostate cancer cells, and characterized how IKKε depletion affects tumor growth and IL-6 tumor secretion in vivo through a mouse xenograft-based approach." (PMID 27577074, 2017). "IL-6 rs1800795 polymorphism showed an increasing effect on the risk of prostate cancer in total analysis, but such influence had no statistical significance, even in stratified analysis by control source." (PMID 28296724, 2017). "High levels of IL-6 expression is detected in patients with prostate cancer which could activate IL-6 receptor, leading to increased STAT3 activation." (PMID 28467474, 2017). "These combined results suggest that suppression of IL-6 levels may be a potential therapeutic strategy for treating prostate cancer." (PMID 27129164, 2016).
prostate carcinoma (continued). "However, there is a controversial observation on regulatory sites using IL-6 autocrine human prostate cancer cells." (PMID 28066415, 2016). "Elevated NF-κB and IL-6 levels have been correlated with drug resistance of prostate cancer cells." (PMID 27129164, 2016). "Pro- or anti-proliferative effects of IL-6 on prostate cancer cells may thus depend on the cellular microenvironment." (PMID 26871479, 2016). "Although STAT3 and IL6 have a definite impact on prostate cancer, because of the intrinsic molecular heterogeneity of prostate cancer, their role might be condition and stage dependent." (PMID 28005952, 2016). "Clinical trials reported that antibody-targeted IL-6 therapy may be useful for improving the performance of other chemotherapy agents during treatment of metastatic castration-resistant prostate cancer." (PMID 27129164, 2016). "IL-1α and IL-6 were up-regulated in prostate cancer samples." (PMID 26683658, 2015). "Also, IL-6 affects PDCD4 expression throughout the development of prostate cancer in both androgen-dependent prostate cancer and androgen-independent prostate cancer." (PMID 26252635, 2015). "It is of note that STAT3 inhibition abrogate IL-6-dependent conversion of ALDH (low) prostate cancer cells to ALDH(high) whereas STAT3 activation induces a melanoma-initiating cell phenotype that could favor chemotherapy resistance and relapse." (PMID 26486080, 2015). "IL-6 and IL-8 produced by prostate cancer cell promote cancer cell proliferation and invasion." (PMID 26682253, 2015). "While all adipose tissue may produce soluble mediators, it may be the local mediators such as IL-6 regulated pathways released by the periprostatic adipose tissue that ultimately have an impact on prostate volume and prostate cancer pathogenesis." (PMID 24731303, 2014). "Since IL-6 was shown to activate AR signaling, increased levels of IL-6 during androgen deprivation may enhance the survival and proliferation of prostate cancer cells." (PMID 24296978, 2014). "One report revealed the important roles of endothelial cells within the prostate cancer microenvironment to promote the prostate cancer metastasis and provide new potential targets of IL-6-- > AR-- > TGFbeta-- > MMP-9 signals to battle the prostate cancer metastasis." (PMID 24397471, 2014). "The present study suggests that the IL-6 signaling pathway may be a useful target for the prevention of androgen-dependent prostate cancer progression to androgen-independence." (PMID 24296978, 2014). "However, in some high-grade tumors, ANXA2 facilitates the adhesion-dependent or -independent growth of prostate cancer through the MAPK pathway or interleukin-6 (IL-6) secretion." (PMID 24591759, 2014). "In terms of prostate cancer, IL-6 has been demonstrated to be able to induce androgen receptor expression and promote tumor progression, thus deemed as a growth factor for most prostate cancer cells in vitro." (PMID 24664372, 2014). "Prostate cancer cell lines are known to produce varying amounts of IL-6." (PMID 23977098, 2013). "We reported previously that MDSCs might be responsible for tumor promotion by IL-6 in prostate cancer." (PMID 23806095, 2013). "IL6 was increased in the serum of men with advanced prostate cancer." (PMID 23342084, 2013). "Androgen-refractory prostate cancer cells have been shown to produce detectable amounts of IL-6." (PMID 24168453, 2013). "Therefore, treatment with concurrent IL-6 inhibition is a potential therapeutic strategy for increasing the radiation response of prostate cancer." (PMID 23806095, 2013). "Thus, it is possible that one of the reasons for the downregulation of let-7 in cancer-associated MSCs is increased LIN28 activity through the positive feedback loop of IL-6 that is initiated by prostate cancer cells." (PMID 23977098, 2013).
prostate carcinoma (continued). "In addition, OSM, along with LIF and IL-6, was detectable by immunohistochemistry in benign prostatic hyperplasia but expressed at increased levels in higher grade prostatic carcinoma." (PMID 24381786, 2013). "Moreover, we identified a positive correlation between circulating IL-6 level and tumor regrowth in irradiated mice with prostate cancer." (PMID 23806095, 2013). "Both OSM and IL-6 could stimulate the proliferation of prostate cancer 22Rv1 cells and stimulate u-Plasminogen Activator and VEGF in DU-145 prostate cancer cells." (PMID 24381786, 2013). "IL-6 may induce the development of melanoma, renal cell carcinoma, ovarian carcinoma, multiple myeloma, prostate carcinoma and breast cancer." (PMID 24168453, 2013). "Pretreatment of LNCaP cells with SB-202190 could inhibit androgen receptor mediated activation of the PSA promotor by IL-6, a factor which is known to promote prostate cancer growth." (PMID 23840550, 2013). "This investigation of the role of IL-6 in prostate cancer might lead to new strategies of enhancing the radiation response of prostate cancer." (PMID 23806095, 2013). "The highest IL6 levels were observed for hMSCs differentiated into osteoblasts and thus may represent a positive feedback loop between prostate cancer cells and hMSCs." (PMID 22870197, 2012). "Initiation and progression of prostate cancer are stimulated by IL-6." (PMID 22792137, 2012). "Our findings show that SNPs in genes from adipokine pathways (leptin, interleukin-6, fibroblast growth factor 2, osteopontin, and insulin growth factor) may influence the development of prostate cancer and aggressive disease." (PMID 22792137, 2012). "In fact, IL-6 expression increased in prostate cancer in comparison with normal tissue." (PMID 22046506, 2012). "We therefore examined whether activation of STAT3 via IL-6 stimulation led to repression of Necdin expression in the prostate cancer cell lines DU145 and PC3." (PMID 22046235, 2011). "IL-6 gene was previously found to be expressed by prostate cancer cells." (PMID 21943235, 2011). "Moreover, STAT3 has been suggested to be involved in IL-6-induced resistance to β-lap in prostatic cancer cells." (PMID 21738692, 2011). "Interestingly, both IL-6 and IL-8 have been suggested as contributors to prostate cancer development." (PMID 20420679, 2010). "In vitro experiments have shown that IL-6 may play a role in prostate cancer cell growth and differentiation and that it stimulates cell growth of malignant cells." (PMID 20420679, 2010). "Collectively, these findings strongly suggest that IL-6 may exert various effects on changes in the phenotype of prostate cancer cells through different molecular mechanisms according to the manner of secretion." (PMID 19844233, 2009). "Furthermore, few studies have investigated the crosstalk between AR and IL-6 secreted in an autocrine manner in prostate cancer cells." (PMID 19844233, 2009). "However, the reported actions of IL-6 in conferring malignant phenotype to prostate cancer cells remain controversial, with some studies showing positive findings, and others showing negative findings." (PMID 19844233, 2009). "To date, however, it remains controversial whether IL-6 confers a malignant phenotype on prostate cancer cells, particularly under an androgen-deprived condition." (PMID 19844233, 2009). "In prostate cancer cells, NFκB may promote cell growth and proliferation by regulating expression of genes such as c-myc, cyclin D1, and IL-6, and inhibit apoptosis through activation of expression of anti-apoptotic genes, such as Bcl-2 and Bcl-XL." (PMID 18226269, 2008). "For example, EGF, transforming growth factor α, insulin-like growth factor 1, interleukin 6, keratinocyte growth factor, and other fibroblast growth factor family members are expressed in advanced prostate cancers and are believed to be important in fueling androgen-independent growth." (PMID 17384772, 2007).